IL6 (interleukin 6)
Diseases named in the same sentence as IL6 in open-access papers (continued):
Sharing a sentence is not in itself a finding about the gene and the disease.
cardiac hypertrophy (continued). "Hirudin can be highly bound to STAT3, IL-6, and MAPK1 and found by molecular docking, which may be the basis for its inhibitory effect on myocardial hypertrophy." (PMID 35784743, 2022). "After the gene was knocked out, it reduced cardiac-related inflammatory factors such as IL-6 and IL-1β, TNF-α and so on, which may be mainly through NF-κB and MAPK signaling pathways to regulate the production of myocardial hypertrophy." (PMID 36064568, 2022). "Proinflammatory cytokines, including IL-6, IL-1β, IFN-γ, IL-17, and TNF-α, could induce cardiac hypertrophy, fibrosis, and apoptosis and further induce inflammation, ultimately resulting in HF." (PMID 35669500, 2022). "We found that down-regulated PTEN was reversed by orexin B, and the enhanced type I and type III collagen, TGF-β, IL6, p-STAT3, STAT3 were also reversed by orexin B, suggesting PTEN was involved in the overexpression of miR-320-induced cardiac hypertrophy and fibrosis in vitro." (PMID 34582362, 2021). "However, myocyte-derived HSP90 exerted a profibrotic role through orchestrating the synthesis of IL-6 and activating STAT-3 in fibroblasts, leading to excess collagen secretion and deposition, thus exaggerating cardiac hypertrophy and fibrosis." (PMID 34485413, 2021). "(P < 0.05) These results suggested that overexpression of miR-320 might heighten TGF-β, IL-6, p-STAT3 and suppress PTEN in cardiac hypertrophy and fibrosis." (PMID 34582362, 2021). "On the contrary, cardiac hypertrophy was not improved in IL-6 knockout mice under Ang II and high salt stimulation." (PMID 33324685, 2020). "It has been shown that EA could attenuate the elevated blood pressure and be of benefit in restoring cardiac hypertrophy in SHR by enhancing NO/NOS activity and reducing the level of IL-6, STAT3, BNP, and so on." (PMID 28293268, 2017). "IL-6 also activates ERK1/2 through the gp130 receptor and promotes cardiac hypertrophy, but inhibits cardiomyocyte apoptosis; increasing IL-6 levels may also accelerate the hypertrophic response in addition to the direct effect of PTX3." (PMID 23372656, 2013). "Garlic oil treatment significantly inhibited the up-regulation in MAPK (e.g., p38, JNK and ERK1/2) and IL-6/MEK5/ERK5 signaling pathways in the diabetic rat hearts, reducing the levels of cardiac pathologic hypertrophy markers such as ANP and BNP, and improving the cardiac contractile function." (PMID 21792366, 2011). "In mouse and human models of pathological myocardial hypertrophy leading to cardiac dysfunction, ERK1/2, SAPK/JNK, and p38 MAPK are activated and increased in the heart, and these pathways further increase the expression of inflammatory mediators (TNF, IL-6) and hypertrophic factors (ET-1)." (PMID 40997050, 2025). "In addition, Ang II can induce Toll-like receptor phosphorylation of STAT3, increase IL-6 production, and continuously activate the JAK/STAT pathway, thereby providing positive feedback and promoting myocardial hypertrophy, fibrosis, and ventricular remodeling." (PMID 38495094, 2024). "Additionally, stretching cardiac fibroblasts was observed to induce low levels of IL-1β secretion; although these levels were insufficient to induce IL-6 production, these were enough to stimulate insulin-like growth factor-1 (IGF-1) for the induction of cardiac hypertrophy." (PMID 38256155, 2024). "Therefore, Cad-11 activates fibroblasts to produce IL-6 which in turn stimulates cardiomyocytes through paracrine means; with subsequent activation of MPAK and CaMKII-STAT3 pathways in the cardiomyocytes that leads to cardiac hypertrophy." (PMID 37047522, 2023). "Depletion of IL-6 can alleviate cardiac hypertrophy induced by Ang II and noradrenaline." (PMID 37047522, 2023). "More recently, deletion of IL-6 was reported to inhibit cardiac inflammation, fibrosis, and dysfunction in an angiotensin II (AngII) and high salt-induced model of hypertension, without affecting cardiac hypertrophy." (PMID 30619368, 2018).
cardiac hypertrophy (continued). "Finally, administration of anti-IL-6 antibody abolished an increase in tyrosine phosphorylation of STAT3, a major signaling molecule downstream of IL-6, in the transgenic mouse heart and prevented development of cardiac hypertrophy in transgenic mice." (PMID 28771545, 2017). "Although the precise mechanisms of Li-Fu formula on reducing IL-6 expression merit further investigations, these findings indeed demonstrated that Li-Fu formula has the effect against cardiac hypertrophy by attenuating non-cardiomyocyte proliferation related p-ERK cascade but not P38 or JNK cascade." (PMID 21785627, 2011). "Furthermore, the up-regulated type I and type III collagen, IL6, TGF-β, and down-regulated PTEN were also reversed by inhibitor BP-1-102 in miR-320 mimic, suggesting STAT3 was involved in the overexpression of miR-320-induced cardiac hypertrophy and fibrosis in vitro." (PMID 34582362, 2021). "The expression levels of cardiac hypertrophy markers (ANP, BNP, and β-MHC) and inflammatory factors (IL-1β and IL-6) increased in the model, the mir-30b-5p-non-loaded, and the mir-30b-5p-loaded groups (p < 0.05)." (PMID 34658880, 2021). "However, compared with the model and mir-30b-5p-non-loaded NPs, the expression of cardiac hypertrophy markers (ANP, BNP, and β-MHC) and inflammatory factors (IL-1β, IL-6) were significantly decreased (p < 0.05)." (PMID 34658880, 2021).
lymphoma (177 papers, 2009 to 2026). A malignant (clonal) proliferation of B- lymphocytes or T- lymphocytes which involves the lymph nodes, bone marrow and/or extranodal sites. "Herein, we developed gene therapeutic forms of sgp130 variants and evaluated the anti-IL-6 potency using a human IL-6-dependent lymphoma cell line in cell culture and xenograft tumor models." (PMID 38980514, 2025). "In lymphoma, pyrexia is a paraneoplastic effect thought to be associated with the release of cytokines such as IL-6 and TNF-α, and those cytokines were manifestations of tumor-related inflammation." (PMID 37909016, 2023). "IL-6 and IL-10 are closely associated with the severity and treatment efficacy in adults with lymphomas who develop infections after chemotherapy and can help distinguish between G- and G+ bacterial infections at an early stage." (PMID 35432366, 2022). "For lymphoma, a key clinical study highlighted the role of IL‐6 in causing anorexia and cachectic state that improved after treatment with anti‐IL‐6 monoclonal antibodies." (PMID 35398917, 2022). "Although IL-6 is associated with lymphoma proliferation and poor prognosis, it is reported that IL-6 can prevent apoptosis of T cells by upregulation of Bcl-2 and promote T cell proliferation via the TCR pathway." (PMID 35818037, 2022). "Eμ-myc mice typically develop aggressive B-cell lymphomas at an early age, and loss of IL-6 delayed the development of these MYC-driven lymphomas." (PMID 33651821, 2021). "Accordingly, the loss of IL-6 selects for Eμ-myc lymphomas at a later stage of differentiation and with a longer latency." (PMID 33651821, 2021). "The loss of IL-6 in MYC lymphomas also leads to a compensatory increase in proteins expressed in the mTOR pathway." (PMID 33651821, 2021). "In contrast, the loss of IL-6 generated Eμ-myc lymphomas at a later stage of B cell differentiation [DLBCL-like], and with a longer latency." (PMID 33651821, 2021). "The expression and secretion of IL-6 and IL-10 as determined by SNP is associated with risk of developing and or OS of lymphomas." (PMID 32046104, 2020). "High serum levels of IL-6 has been associated with a shorter overall survival (OS) and a lower complete response (CS) rate in human lymphoma." (PMID 30987001, 2019). "IL-6 and IL-10 help these cells to evade the immune system's surveillance, thereby causing malignant proliferation of lymphoma cells." (PMID 31852157, 2019). "IL-6–induced STAT3 or STAT5 activation is a critical mechanism underlying PI3K inhibitor resistance in lymphoma, supporting the utility of IL-6 as an effective biomarker to predict therapeutic response to PI3K inhibitors." (PMID 31601188, 2019). "This study further showed that, C/EBPβ controlled-lymphoma-associated C/EBPβ competent DCs expressed high levels of IL-10 and IL-6." (PMID 30544623, 2018). "In primary effusion lymphoma, which is also considered to be derived from plasmablasts, KSHV-encoded viral IL-6 is secreted from lymphoma cells and induces the proliferation of the tumour by an autocrine mechanism." (PMID 28860565, 2017). "Taken together, the findings in the intercrossed dnTGFβRII IL-6−/−, dnTGFβRII p40−/− and dnTGFβRII mice indicate that dnTGFβRII homozygosity is associated with occurrence of lymphoma-like T cell infiltration." (PMID 23145171, 2012). "IL-6 signaling is presumed to be associated with the development of lymphoma, and it has been suggested that the blockade of IL-6 induced by TCZ might reduce lymphoma development, even among patients with RA taking MTX." (PMID 39860574, 2025). "Notably, we did detect the lymphoma survival factor IL-6 in the lumen and associated reservoirs of the lymphoma-on-chip model only when FRCs were present in the hydrogel and LECs in the lumen." (PMID 40061210, 2025).
lymphoma (continued). "The major cytokine released by adipocytes is interleukin (IL)-6, which could increase the risk of different cancers in obese patients, such as breast, liver, prostate, colon, and esophagus cancers, and lymphomas." (PMID 36555171, 2022). "Whereas control IL6+/+;Eμ-myc mice developed lethal lymphomas with the expected latency [mean survival 103+/-46 days] and full penetrance [100% tumor incidence], the loss of IL-6 significantly delayed lymphomagenesis, extending tumor-free survival by 40% [164+/-99 days, p = 0.0031]." (PMID 33651821, 2021). "Thus, the loss of IL-6 extends the Eμ-myc lymphoma development to a later stage of B cell differentiation with a longer latency." (PMID 33651821, 2021). "In leukemia patients, IL6 produced by adult T-cell leukemia/lymphoma cells may cause fever and further activate macrophages to secrete TNF-α, leading to shock and exacerbation of the fever." (PMID 32110485, 2020). "Furthermore, cytokine analysis of IL-10 and IL6 ratios greater than 1.0 are suggested diagnostic criteria for lymphoma." (PMID 29954352, 2018). "Recent studies propose that the T-cell dysregulation associated with Hodgkin’s lymphoma contributes to high rates of pruritus associated with this malignancy and the cytokines IL-6, IL-8, and IL-31 may also play roles in lymphoma-associated or chronic itch." (PMID 28302100, 2017). "Inflammatory cytokines other than IL-6 have been associated with lymphoma pathogenesis." (PMID 29078819, 2017). "Using a receiver operating characteristic analysis to identify threshold values diagnostic for lymphoma, optimal sensitivity and specificity improved to 80.0% and 100%, respectively, for IL-10>7.025 pg/ml and 90.0% and 100.0%, respectively, for IL-10/IL-6>0.02718." (PMID 23750271, 2013). "Lymphoma patients have significantly higher levels of circulating pro- and anti-inflammatory cytokines IL-10, IL-6, and Sema4D as compared to healthy donors." (PMID 42194097, 2026). "IL-6 also promotes PD-L1 increases on macrophages and monocytes, which is predictive of inferior survival for patients with lymphoma." (PMID 40331601, 2025). "It turned out that C5a, TNF-α, growth-related oncogene (GRO)-a, CCL1/I-309, and interleukin-6 significantly promoted the proliferation of lymphoma cell lines when co-cultured with M2 macrophages." (PMID 41030738, 2025). "Studies have demonstrated that estrogen modulates the expression of key cytokines, such as interleukin-6 and tumor necrosis factor-alpha, which contribute to tumor progression and immune evasion in some cancers, including lymphomas." (PMID 39926277, 2025). "Locally, immune cells secrete pro-proliferative cytokines: M2-polarized macrophages produce IL-10, TFH cells secrete IL-21, and Th17 and CD8+ T-cells produce IL-6, collectively supporting lymphoma cell survival and invasion." (PMID 41303704, 2025). "By using an IL-6-dependent lymphoma cell line and xenograft tumor model, we demonstrated the superior inhibitory potential of second-generation anti-IL-6 trans-signaling therapeutic." (PMID 38980514, 2025). "Among these, most notably IL-6 play a central role in establishing and maintaining an inflammatory milieu that supports lymphoma cell survival and progression." (PMID 41303704, 2025). "The results showed that soluble CD23 significantly increased in individuals who developed lymphoma, while IL-6 was categorically elevated among those who developed BL." (PMID 40422208, 2025). "Detection of cytokines such as IL-10/IL-6 plays an important role in assisting the diagnosis and treatment of lymphomas in special locations." (PMID 40842532, 2025). "Expanding on the analysis of performance against lymphoma cell lines, we studied the secretion of IL-2 and IL-6 by CAR/CCR and CAR T cells." (PMID 38340727, 2024).
lymphoma (continued). "The expressions of IL-4 and IL-6 in KO + lymphoma cell group were significantly inhibited compared with WT + lymphoma cell group, demonstrating that Notch-1 is a key upstream molecule regulating the expressions of IL-4 and IL-6." (PMID 38261741, 2024). "The expression levels of IL-4 and IL-6 were low in WT group and KO group, but they significantly increased in WT + lymphoma cell group, suggesting that lymphoma cells can activate IL-4 and IL-6 in bone marrow-derived macrophages." (PMID 38261741, 2024). "Previous CD19 CAR T cell studies in lymphoma demonstrated a significant association between CRS/ICANS and elevated levels of cytokines, including IFNγ, IL-2, IL-6, IL-8, IL-10, IL-15, and TNFα1,20–22." (PMID 39011120, 2024). "Additional studies are necessary to explore, dissect, and therapeutically perturb the IL-6/JAK/STAT3 pathway in EBV+ lymphomas." (PMID 38915538, 2024). "Diffuse large B-cell lymphoma (DLBCL), the most frequent malignant lymphoma in adults, is characterized by constitutive NF-κB activation and consequently by a constitutive production of interleukin-6 (IL-6) and IL-10." (PMID 38539832, 2024). "The rationale for this investigation stems from EBV’s established role in various cancers, including lymphomas, where it can influence cellular growth factors like IL-6 and potentially angiogenesis through interleukin-8." (PMID 38791038, 2024). "Lymphomas induce an inflammatory state characterized by immune dysregulation and the release of pro-inflammatory cytokines, such as interleukin-6 (IL-6), IL-10, and tumor necrosis factor-alpha (TNF-α), which are associated with the development of NHL." (PMID 39110199, 2024). "When IXA4 was used, the expressions of IL-4 and IL-6 were upregulated in WT + lymphoma cell + IXA4 group compared with WT + lymphoma cell group." (PMID 38261741, 2024). "Increased levels of IL-6, the major upstream cytokine to activate STAT3, are also associated with a poor lymphoma prognosis." (PMID 37686472, 2023). "Consistent with lymphoma and other reports, IL-6 was the most dominant of all markers; our findings provide insight into the availability of IL-6 in AA for predicting bacterial lung infection." (PMID 36319826, 2022). "In this study, for the first time, we proposed the combination of IL-6 and IL-10 to identify G-/G+ bacterial infections in adult lymphoma during the myelosuppression stage after chemotherapy." (PMID 35432366, 2022). "In competitive binding assay, lymphoma cells in experimental group were co-cultured with UCMSCs-Tandab(IL-6/CD20) in a transwell system for 24 h and then the cells were incubated with anti-human CD20 antibody and analyzed by flow cytometry." (PMID 36104733, 2022). "In conclusion, this study suggests that cytokines, especially IL-6 and IL-10, can preliminarily identify lymphoma G-/G+ infections, which is conducive to early, timely and targeted selection of antibiotics." (PMID 35432366, 2022). "SYK can also be activated by the hematopoietic cell kinase (HCK) in MyD88-mutated lymphoma cells, and, at the same time, HCK can be triggered either by mutated MyD88 directly or through IL-6." (PMID 35628381, 2022). "CCK-8 assay was used to compare the therapeutic effect of the supernatants of UCMSCs-Tandab(IL-6/CD20) against lymphoma cells with rituximab, tocilizumab and rituximab + tocilizumab in vitro." (PMID 36104733, 2022). "For example, in Burkitt’s lymphoma, the use of doxorubicin treatment can cause the thymus to release IL-6 and tissue inhibitor of metalloproteinase 1 (TIMP1), causing the remaining lymphoma tissue to resist the drug, which leads to the recurrence of lymphoma." (PMID 35668934, 2022). "As a hallmark of SS, B-cell hyperactivity causes hypergammaglobulinemia, autoantibody production, increased serum interleukin-6 (IL-6), IL-17, IL-21, IFN-α levels, and an increased risk of lymphoma, particularly B-cell-derived non-Hodgkin lymphomas." (PMID 35665339, 2022).